EGFR (epidermal growth factor receptor)
Diseases named in the same sentence as EGFR in open-access papers (continued):
Sharing a sentence is not in itself a finding about the gene and the disease.
colorectal cancer (continued). "Epidermal growth factor receptor inhibitor therapy is now approved for treatment of metastatic colorectal carcinomas (CRC) in patients with tumors lacking KRAS mutations." (PMID 21122130, 2010). "Based on these findings we investigated the correlation between both FISH and CISH EGFR GCN and clinical outcome in K-RAS wild-type colorectal cancer treated with irinotecan-cetuximab." (PMID 19712476, 2009). "As we have seen, molecular drivers that determine sensitivity to EGFR inhibitors in esophageal and GEJ adenocarcinomas are different from those important in lung and colorectal cancers." (PMID 19636422, 2009). "We designed a multicentre phase II study in advanced colorectal cancer combining gefitinib+FOLFOX in order to determine the activity and to relate EGFR expression and gene amplification and NF-kB activation to therapeutic results." (PMID 18059397, 2008). "The finding that Id-1 had effects on the molecules EGFR and VEGF in colorectal carcinomas is important in that these two molecules have been considered as new therapeutic targets for many advanced tumours recently." (PMID 19014499, 2008). "In colorectal carcinoma (CRC) patients, EGFR is over-expressed in 75% of the tumors and its over-expression is associated with worse outcome." (PMID 18700047, 2008). "Using human colorectal cancer (CRC) cells, we evaluated the involvement of the insulin receptor isoform-A (InsR-A) in de novo resistance to gefitinib, an EGFR tyrosine kinase inhibitor." (PMID 16819546, 2006). "However, colorectal cancer demonstrated intrinsic resistance to MRTX1133, primarily due to the feedback activation of the EGFR pathway." (PMID 41604371, 2026). "These included stellate cell activation and liver fibrosis, multiple TGF-β-driven programs (stimulation in lung, breast, pancreatic, and colorectal cancers; SMAD signaling; Activin A signaling; and EMT induction), and EGFR- and WNT/β-catenin-mediated transcriptional regulation." (PMID 41399370, 2026). "This approach is supported by recent studies using the fluorescence-Raman endoscopic system (FRES) for the simultaneous detection of EGFR and VEGF in colorectal cancer, which demonstrated the importance of considering both tumor cells and their microenvironment." (PMID 41550766, 2026). "Thus, Aux-COPII-CAM and Aux-EGFR will be promising biomarkers for colorectal cancer diagnosis, while targeting JAK/STAT and EGFR signaling will be an effective treatment of colorectal cancer." (PMID 40825946, 2025). "Additionally, the expression levels of RHBDD1 were found to positively correlate with the activation of the EGFR/Raf/MEK/ERK signaling cascade, a crucial pathway driving colorectal cancer development." (PMID 40787199, 2025). "Moreover, a mutant SMARCA4R enhances the SWI/SNF complex’s ATPase activity, facilitating chromatin remodeling, which reinforces EGFR and TNS4 transcriptional expression, promoting proliferation in colorectal cancer cells and patient-derived tumor organoids." (PMID 40906372, 2025). "In addition, combination therapy and antibodies that target the epidermal growth factor receptor (EGFR) and vascular endothelial growth factor receptor (VEGFR) are used to treat selected patients with colorectal cancer." (PMID 40649987, 2025). "HER2 Amplification for Colorectal Cancer Enhanced Stratification (HERACLES) was an important phase II study as it proved the concept that blockade of HER2 can be achieved by trastuzumab and lapatinib (a dual EGFR and HER2 TKI) in HER2-positive mCRC." (PMID 40940907, 2025). "Additionally, thymol exhibits anti‐EGFR activity, while carvacrol modulates the HIF‐1α/VEGF pathway, making them potential candidates for colorectal cancer (CRC) management." (PMID 40964147, 2025). "In addition, indoxyl sulfate can activate the aryl hydrocarbon receptor and Akt signaling pathways, inducing epidermal growth factor receptor (EGFR) expression and promoting colorectal cancer progression." (PMID 41257289, 2025).
colorectal cancer (continued). "Additionally, SMARCA4 recruited by PRMT1-mediated H4R3me2a enhances EGFR signaling and TNS4 expression in colorectal cancer, with elevated PRMT1 or SMARCA4 levels positively correlating with increased EGFR and TNS4 expression and decreased overall survival." (PMID 40906372, 2025). "While KRAS/NRAS mutations are well known to predict a lack of efficacy from anti-EGFR antibodies in colorectal cancers, studies investigating the addition of the EGFR TKI erlotinib to chemotherapy in advanced BTC and PDA suggested a similar pattern." (PMID 40507311, 2025). "Research has suggested that PSP may serve as a prophylactic and therapeutic agent against colorectal cancer (CRC) by down-regulating the programmed cell-death ligand 1 (PD-L1) and epidermal growth factor receptor (EGFR) signaling pathways." (PMID 40507156, 2025). "In colorectal cancer, for instance, B-RAF inhibitors alone are ineffective due to EGFR reactivation, but the combination of B-RAF + MEK + EGFR inhibitors has demonstrated significant survival benefits, underscoring the necessity of combination regimens in certain tumor types." (PMID 40141317, 2025). "In the specific context of colorectal cancer, we observed reduced phosphorylation of EGFR and MET following lovastatin treatment, but no significant changes in SRC phosphorylation." (PMID 40832614, 2025). "Therefore, a combination therapy targeting both EGFR and KRASG12C was proposed to overcome resistance to KRASG12C blockade in colorectal cancer." (PMID 40141164, 2025). "Moreover, HTyr was shown to reduce the levels of epidermal growth factor receptor (EGFR) in HT‐29 xenografts and colorectal carcinoma cells." (PMID 40979569, 2025). "EGFR overexpression was identified in the majority (87.4%) of AAC patients, which represents a higher proportion compared to the approximately 25–75% observed in colorectal cancers and about 45% in pancreatic ductal adenocarcinoma." (PMID 39123483, 2024). "In studies of gastric cancer and colorectal cancer, it is inclined to think that Kep and Ktrans were significantly correlated with the expression of EGFR33,34, indicating that Kep and Ktrans have statistical significance in the expression of EGFR." (PMID 38396128, 2024). "The EGFR-directed QDMs containing Bcl2 siRNA, so-called immuno-QDM/siBcl2 (iQDM/siBcl2), exhibited the more effective delivery of QDs and siBcl2 to target human colorectal cancer cells in cultures as well as in mouse xenografts." (PMID 38892434, 2024). "In colorectal cancer, OGN reversed EMT and invasive abilities through the EGFR/Akt pathway." (PMID 38402185, 2024). "The meta-analysis supports the use of EGFR mAbs in the treatment of mCRC without mutations in KRAS, particularly for left-sided colorectal cancer and where the tumour does not harbour NRAS or BRAF mutations." (PMID 38402342, 2024). "Therefore, exploring the interaction mechanisms between EGFR and PLD2 in colorectal cancer liver metastasis is of great significance for cancer biology research and the formulation of clinical treatment strategies." (PMID 39581873, 2024). "Metastatic colorectal cancers, for example, show a response rate of only 5–10% to BRAF-inhibitors, which has been suggested to be attributed to a higher signaling through EGFR in response to BRAF-inhibitors." (PMID 38716076, 2024). "In addition, colorectal cancer is characterized by strong adaptive feedback mechanisms in response to RAS pathway inhibition, mostly mediated via the EGF receptor (EGFR)." (PMID 38593348, 2024). "Our work began with computational studies of public data identifying a strong negative correlation between ZNRF3/RNF43 mRNA levels and EGFR protein expression in datasets of human adrenocortical carcinomas and colorectal cancers." (PMID 38260423, 2024).
colorectal cancer (continued). "We then tested OLN's efficacy on the viability of isogenic colorectal cancer cell lines, LIM1215 WT and R4, which are sensitive and resistant to Cetuximab (an anti-epidermal growth factor receptor therapy) respectively, with the resistant line R4 exhibiting higher GRP78 level." (PMID 39238058, 2024). "The most commonly dysregulated pathways with or lacking mutations in critical genes or proteins in colorectal cancer are the MAPK, EGFR, and Wnt/β-catenin signaling pathways." (PMID 39194723, 2024). "and NSCLC, but not in colorectal cancer due to a feedback upregulation of the epidermal growth factor receptor (EGFR) that necessitates further EGFR blockade." (PMID 37982847, 2024). "However, very limited response to this same drug was observed in colorectal cancer studies that revealed that BRAFV600E tumor cells presented a rapid feedback activation of EGFR expression that mediated resistance to BRAF inhibitors." (PMID 39018564, 2024). "In colorectal cancer, KRAS, NRAS, BRAF, and PIK3CA mutations induce a negative effect on the response to anti-EGFR therapies." (PMID 38248103, 2024). "EGFR and its ligands EREG and AREG are commonly overexpressed in colorectal cancer." (PMID 37974093, 2023). "We retrospectively analyzed data of 224 patients with unresectable advanced or recurrent colorectal cancer from the Fukuyama Medical Center for Patients, who were treated with concomitant cytotoxic anticancer drug and VEGF or EGFR inhibitor between April 2016 and October 2021." (PMID 37394446, 2023). "Because KRAS mutations are known to make EGFR inhibitors less effective, KRAS mutations have been tested as a negative selection to predict response to EGFR TKIs in colorectal cancer patients." (PMID 36810451, 2023). "This case highlights that the BRAF non-V600 mutations, such as BRAF p.N581I mutant, may lead to resistance to epidermal growth factor receptor (EGFR) inhibitors and result in a rapid course in colorectal cancer." (PMID 37519790, 2023). "EGFR and ERBB2 expression was mainly measured by immunohistochemistry methods in primary tumours and CRC metastases, whereas ERBB2 and MET expression was measured in colorectal cancer cells in the same population." (PMID 36890818, 2023). "Previous studies found a central role for epidermal growth factor receptor (EGFR), mesenchymal-epithelial transition factor (MET) and insulin-like growth factor 1 receptors (IGFR1) in abolishing RAF inhibitor sensitivity in colorectal cancer and melanoma with BRAFV600E 18-22." (PMID 37325052, 2023). "It is known that EGFR inhibition is not effective in KRAS-mutant colorectal cancers, due to downstream activation of the pathway." (PMID 37190303, 2023). "For example, unlike the EGFR gene expression level itself, which is a poor predictor of cetuximab treatment response in colorectal cancer, a broader view of the quantitively measured activation of relevant molecular pathways has shown promising results." (PMID 38201251, 2023). "Preliminary results showed that more than 50 patients were treated with adagrasib in combination with either pembrolizumab (a PD-1 inhibitor) for NSCLC, cetuximab (an anti-EGFR antibody) for colorectal cancer, or TNO-155 (an SHP-2 inhibitor) for NSCLC or colorectal cancer." (PMID 37662925, 2023). "Notably, in colorectal cancer, BRAF inhibitors show limited efficacy, potentially due to the feedback activation of EGFR, whereas ectopic expression of EGFR in melanoma cells has been shown to elicit resistance to BRAF inhibitors." (PMID 36219477, 2023). "The varied response rates to EGFR-targeted treatment in patients with colorectal cancer (CRC) are explained by the significant intra- and inter-patient heterogeneity in mutant EGFR expression, as well as that of additional genetic changes linked to EGFR inhibition, such as KRAS and PIK3CA mutations." (PMID 38132192, 2023).
colorectal cancer (continued). "Because we and others have ever found that GALNT2 could regulate EGFR and MET phosphorylation which have been demonstrated to modulate colorectal cancer metastasis, we tested if GALNT2 knockout could interfere with their signaling." (PMID 36409270, 2023). "Cetuximab, first described inhibiting EGFR in 1988, was accepted for clinical use in the KRAS wild-type colorectal cancer (CRC) treatment, leading to the first routine genotyping of CRC patients, since somatic mutations of KRAS were found to confer cetuximab resistance." (PMID 35626010, 2022). "In colorectal cancer cell lines, the reduction of ITLN1 expression by short-hairpin RNA increased cell growth and proliferation as well as Akt, extracellular signal-regulated kinase (ERK), and epidermal growth factor receptor (EGFR) phosphorylation." (PMID 35186726, 2022). "In particular, the contribution of the WNT and EGFR pathways, which are both frequently deregulated in colorectal cancer, has not yet been addressed in this context." (PMID 35565214, 2022). "For example, EMT-mediated CXCL1/5 can modulate resistance to anti-EGFR therapy in colorectal cancer, and CXCL1/5 may be a potential serum biomarker for predicting colorectal cancer resistance to EGFR therapy." (PMID 36393968, 2022). "To explore whether EGFR mediated the effects of CB1 on macrophage polarization, we overexpressed EFGR and co-treated with ACEA in colorectal cancer cells." (PMID 35641479, 2022). "Comparison of mRNA levels in a GC data set from the NCBI’s Gene Expression Omnibus (GEO) also revealed positive correlations among CGA, EGFR, and GATA2; intriguingly, positive correlations also were observed in a similar analysis of the GEO colorectal cancer (CRC) data set." (PMID 35289315, 2022). "EGFR is commonly over expressed in colorectal cancer on immunohistochemical analysis; however, it has not been established as an independent prognostic variable." (PMID 35323316, 2022). "Cetuximab: Cetuximab is an EGFR inhibitor, a fully humanized mAB, with FDA-approval for patients with K-Ras wild-type, EGFR-expressing colorectal cancer, metastatic colorectal cancer and advanced squamous cell carcinoma of the head and neck in combination with radiation therapy." (PMID 35757736, 2022). "Rechallenge with EGFR inhibitors represents a promising strategy for patients with RAS wild type (WT) colorectal cancer (CRC) but definitive selection criteria are lacking." (PMID 35530345, 2022). "We developed 89Zr-matuzumab as a PET probe for diagnosis/monitoring of response to treatment of a noncompeting anti-EGFR nimotuzumab antibody drug conjugate (ADC) using mouse colorectal cancer (CRC) xenografts." (PMID 36145664, 2022). "Moreover, EGFR cross talks with integrin αvβ3 signaling to activate ERK1/2 and PD-L1 expression in mutant KRAS colorectal cancer (CRC)." (PMID 35705962, 2022). "However, excessive bile acids, especially cytotoxic DCA, have been proven to destroy intestinal barrier function and promote colorectal cancer progression by inducing oxidative stress, inhibiting FXR signalling, or activating Wnt and EGFR signalling." (PMID 36555220, 2022). "Although drugs targeting HER3 have not been approved for use in colorectal cancer, EGFR targeted therapy is approved such as cetuximab." (PMID 36551663, 2022). "OSI, an irreversible EGFR/HER2 inhibitor, can upregulate the expression of monocarboxylate transporter 1 (MCT1) and then activate LKB1/AMPK signaling, leading to autophagy induction in colorectal cancer cells." (PMID 36080457, 2022). "Subsequently, the positive results from the BEACON CRC (colorectal cancer) trial led the FDA to approve, in 2020, the combination of encorafenib and cetuximab (an anti-EGFR monoclonal antibody) in the setting of pretreated BRAF V600E mutant patients with metastatic colorectal cancer." (PMID 36230797, 2022).
colorectal cancer (continued). "Tjalma and co-workers initially analyzed the specific binding of anti-vascular endothelial growth factor (VEGF) and anti-epidermal growth factor receptor (EGFR) antibodies to hyperplastic (benign) polyps, various types of adenomas and colorectal cancer samples." (PMID 35280747, 2022). "PGE2 promotes colorectal cancer cell invasion via PI3K 71 and EGFR transactivation by SRC." (PMID 36110531, 2022). "In this perspective, a phase Ib/II study with encorafenib+cetuximab (an EGFR-inhibitor) with or without alpelisib (a PI3K-inhibitor) in BRAF-mutant colorectal cancer was conducted." (PMID 34804975, 2021). "That is the case, for instance, with KRAS status, which is a strong biomarker of negative response to EGFR antibodies in colorectal cancer patients." (PMID 33795829, 2021). "The presence of KRAS/NRAS mutations suggests the lack of response to EGFR‐targeted therapies for patients with NSCLC, head and neck cancer or colorectal cancer." (PMID 34658138, 2021). "Notably, PIK3CA mutations have been found to have a synergistic effect with mutational inactivation of PTEN in inducing drug resistance or in inducing poor prognosis with EGFR/KRAS comutations in nonsmall cell lung and colorectal cancer." (PMID 33827485, 2021). "We conclude by explaining why some patients with lung or colorectal cancer do not respond to the anti-EGFR therapies and why still other patients, who initially respond, become tolerant to the drugs." (PMID 34206026, 2021). "Indeed, in colorectal cancer it has been demonstrated that a sub-clone resistant to the EGFR blockade expresses TGF-α, which, by sustaining EGFR/ERK pathways, protects their sensitive counterparts from EGFR inhibitors." (PMID 33803675, 2021). "As a critical element of the mitogen activated protein kinase (MAPK) pathway, RAS is the most common mutated gene in colorectal cancer (CRC), and its occurrence is associated with a lack of response to anti-epidermal growth factor receptor (EGFR) blockade." (PMID 34745987, 2021). "In colorectal cancer, AREG is known to act competitively with anti-EGFR monoclonal antibodies and activate downstream signaling, and thus may be involved with cetuximab resistance." (PMID 34893673, 2021). "Colorectal cancer cells were all highly sensitive to killing by reovirus-activated NK cells regardless of KRAS genotype or EGFR expression level, and reovirus further enhanced NK-cell cytotoxicity against cetuximab-coated colorectal cancer cells." (PMID 33933132, 2021). "Our study also proves that PRMT5 promotes cell proliferation and EMT in human colorectal cancer via activation of the EGFR/Akt/GSK3β signaling axis, but not ERK1/2 or PTEN/mTOR signaling pathways, which is strongly linked to the PRMT5 enzyme activity." (PMID 33495409, 2021). "The SPG20 gene encodes a protein called Spartin that has been found to be involved in intracellular epidermal growth factor receptor trafficking; SPG20 promoter has been found to be hypermethylated in colorectal cancer, resulting in gene silencing and cytokinesis arrest." (PMID 33499054, 2021). "Two years later, targeting of epidermal growth factor receptor (EGFR) in colorectal cancer allowed the discrimination of neoplastic and non-neoplastic tissue areas in living animals and human tissue samples." (PMID 34368180, 2021). "EGFR was furthermore reported to mediate resistance to BRAF inhibitors in melanoma, and the high EGFR expression in colorectal cancer cells is considered to be the reason for the lack of BRAF inhibitor responsiveness of BRAFV600E mutant colorectal cancer." (PMID 33916908, 2021).